MIR4495 (microRNA 4495)
Synonyms: hsa-mir-4495
Gene: MicroRNA gene on chromosome 12 (97,939,056 to 97,939,121, reverse strand). Ensembl gene ENSG00000265861.
Homologues: Orthologues: chimpanzee MIR4495 (100% identical).